HOXB9 (homeobox B9)
Diseases named in the same sentence as HOXB9 in open-access papers (continued):
Sharing a sentence is not in itself a finding about the gene and the disease.
tumor (continued). "Various tumor growth and angiogenic factors including VEGF (vascular endothelial growth factor), bFGF (basic fibroblast growth factor), TGF-β (transforming growth factor β) and NRG2 (neuregulin 2) are regulated by HOXB9 in a variety of cancers." (PMID 28514754, 2017). "Only minimal decreases in MVD and increases in the extent of pericyte coverage of residual blood vessels were observed in tumours expressing both EGR1 and HOXB9 after the miR-192 treatments, emphasizing the key roles EGR1 and HOXB9 play in mediating the anti-angiogenic effects of miR-192." (PMID 27041221, 2016). "The hexapeptide motif of HOXB9 was determined to inhibit its MET induction and tumor suppression in GC cells, suggesting that this motif contributes to the oncogenic role of HOXB9 instead of tumor suppression." (PMID 26536658, 2015). "In normal tissues, expression of HOXB9 was expressed at low levels, confined to the nuclei of the basal and spinous layers, whilst in HNSCC the nuclear intensity increased, with a greater proportion of cells in tumour nests expressing HOXB9." (PMID 25860510, 2015). "HOXB9 and PHF20L1 are members of gene families that are fused in other neoplasms." (PMID 23260012, 2012). "To investigate the mechanisms underlying the role of HOXB9 in PCa metastasis, we examined the effects of HOXB9 on the expression of a panel of representative genes from the top two DEG categories, namely tumour metastasis- and CSC growth-related genes, in orthotopic implantation tumours." (PMID 34247196, 2021). "Using an in vitro BBB model, knockdown and overexpression experiments showed that HOXB9-dependent expression of MMP9 in NSCLC cells leads to reduced expression of junctional proteins in cultured human vascular endothelial cells and enhanced transmigration of tumor cells." (PMID 33411683, 2020). "Thus, HOXB9 activates the WNT signaling pathway and enhances the acquisition of capabilities critical to the transformation of normal cells to cancer, including EMT and the growth of new vasculature within the tumor microenvironment." (PMID 32104178, 2020). "Finally, the levels of EREG and HOXB9 were examined in the matched tumor and non-tumor tissues of CRC patients." (PMID 29199273, 2017). "Simultaneously, the HOXB9 protein also has MET induction activity that is mediated by other regulatory sites and may function in gastric tissue differentiation, which also gives HOXB9 tumor suppression activity." (PMID 26536658, 2015). "These tumor growth and angiogenic factors were upregulated in GC cells lacking HOXB9." (PMID 26536658, 2015). "Given that both HOXB9 and miR-196a are highly expressed in HNSCC we assessed the phenotypic consequences of this in OPM and HNSCC cells, particularly assessing features that promote the ability of the cells to proliferate and to spread, enhancing the development of the tumour." (PMID 25860510, 2015). "Therefore, re-expression of HOXB9 in GC cells induced MET and tumor suppression." (PMID 26536658, 2015). "However, when overexpressing a HOXB9 mutant lacking the hexapeptide motif, a more potent MET induction and tumor suppression was observed compared to that of the wild-type, indicating that the presence of the hexapeptide motif reduced HOXB9 MET induction and tumor suppression activity." (PMID 26536658, 2015). "Our study which compared co-culture with mono-culture demonstrated that tumorigenic effects of HOXB9 in the microenvironment resulted in the enhanced release of various cytokines and that IL6 release from tumor microenvironment plays an important role in tumor proliferation." (PMID 24885802, 2014).
tumor (continued). "Moreover, mouse xenograft assays using the Ishikawa stable cell lines infected with lentiviruses carrying control shRNA or HOXB9 shRNA showed that cells expressing sh-HOXB9 displayed no significance in tumor growth rate and tumor volumes than that of the control group." (PMID 29724991, 2018). "HOXB9 mRNA expression is reduced in some PBX1-expressing GC tissues, and the occurrence of a moderately diminished relationship between PBX1 and HOXB9 expression indicates that PBX1 and HOXB9 may be considered tumor markers when attempting to determine GC malignancy." (PMID 28514754, 2017). "Orthotopic tumour models were developed from CD44+, CD44+ α2β1+, ALDH+ CD44+ α2β1+ and ALDH+ CD44+ CXCR4+ CD24+ cells with or without HOXB9 knockdown." (PMID 34247196, 2021). "In contrast, the tumours expressing EGR1 and HOXB9 proteins failed to respond to miR-192 therapy, again demonstrating the central role of these two proteins in miR-192-mediated anti-tumour effect." (PMID 27041221, 2016). "In the tumors of the HOXB9 OE/SKOV3-injected group, however, the inhibiting effects of cisplatin on tumor progression were not significant (tumor weight, 1186.0 mg ± 473.2 mg vs. 1156.7 mg ± 401.0 mg; tumor volume, 2159.4 mm3 ± 75.4 mm3 vs. 1807.1 mm3 ± 183.3 mm3; p > 0.05 for both)." (PMID 36674764, 2023). "Therefore, when the hexapeptide motif is not present, HOXB9 achieves more potent MET induction and tumor suppression activity in GC cells as what been observed in the present study." (PMID 26536658, 2015). "When HOXB9 lacked a hexapeptide motif, it induced more potent MET and tumor suppression." (PMID 26536658, 2015).
cancer (47 papers, 2010 to 2025). A tumor composed of atypical neoplastic, often pleomorphic cells that invade other tissues. "HOXA5 affects apoptosis, differentiation, and cell proliferation in cancer, whereas HOXB9 expression is associated with immune response and prognosis in a variety of cancers." (PMID 40305321, 2025). "As genetic mutations are associated with poor prognosis in cancer patients, we analyzed the gene alteration of HOXB9 in EC samples from the cBioPortal database." (PMID 36803556, 2023). "Our pan-cancer analysis indicates that in the majority of cancers, there is a strong correlation between HOXB9 expression and the mutation levels of MMR genes." (PMID 37301547, 2023). "The results of these analyses also demonstrated that most cancer types have identified HOXB9 as a risk factor." (PMID 37301547, 2023). "Lastly, the integration of ImmuneScore, EstimateScore, StromalScore, and neoantigens led to the observation that HOXB9 is linked to immune infiltration in certain types of cancer." (PMID 37301547, 2023). "In summary, our findings propose that HOXB9 displays abnormal expression across diverse types of cancer, potentially establishing it as a novel cancer biomarker for future diagnostic and prognostic applications." (PMID 37301547, 2023). "Specifically, elevated HOXB9 expression was identified as a significant risk factor for a considerable proportion of cancer types." (PMID 37301547, 2023). "An increasing number of studies demonstrated that HOXB9 was associated with resistance to chemotherapy in other cancers." (PMID 36674764, 2023). "An increasing number of studies demonstrate that the HOXB9 gene is associated with cancer progression and resistance to chemoradiation." (PMID 35634239, 2022). "Numerous recent studies have underlined the central role of HOXB9 in promoting cancer progression, metastasis, and resistance to anti-angiogenic treatments." (PMID 33171691, 2020). "Besides, HOXB9 expression was closely associated with immune cell infiltration and checkpoint genes in many cancers." (PMID 37301547, 2023). "We found the five MMR genes were associated with HOXB9 and reached a significant correlation in some cancers, which may suggest that MMR may have a potential role in regulating tumorigenesis by reducing the rate of DNA replication errors." (PMID 37301547, 2023). "HOXB9 is also directly associated with cancer-induced patient mortality." (PMID 32104178, 2020). "To summarize, HOXB9 has been extensively studied in relation to cancer progression and is considered a crucial player in this process." (PMID 37301547, 2023). "The Homeobox B9 gene belonged to the HOX family and was implicated in molecular regulatory processes in many cancers." (PMID 37301547, 2023). "The HOXB9 gene, which plays a key role in embryonic development, is also involved in the regulation of various human cancers." (PMID 36803556, 2023). "We performed Kaplan-Meier survival analysis to investigate the impact of HOXB9 on patient prognosis in different cancer types using patients’ data dichotomized for median gene expression level." (PMID 37301547, 2023). "TIMER 2.0 database was used to explore the correlation between HOXB9 expression and immune infiltration multiple cancers." (PMID 37657018, 2023). "In general, the results were the same for cancer types with high and low HOXB9 expressions in both databases." (PMID 36803556, 2023). "The divergent functions of HOXB9 in different types of cancer suggest that the development and progression of cancer are complex processes, and the heterogeneity of cancer tissues should be taken into consideration in specific contexts." (PMID 37301547, 2023).
cancer (continued). "We combined the TCGA and GTEx databases to examine the expression patterns of HOXB9 across various types of cancer." (PMID 37301547, 2023). "We reveal the association of HOXB9 with evaluation indicators of pan-cancer, such as immune infiltration, immune checkpoint genes (ICGs), TMB, MSI, MMR, and DNA methylation in pan-cancer." (PMID 37301547, 2023). "The first step of our study involved analyzing multiple databases to investigate the expression levels and clinical significance of HOXB9 in 33 different types of cancer." (PMID 37301547, 2023). "In conclusion, our study provides a comprehensive analysis of the role of HOXB9 in various cancers and suggests that it has the potential to serve as a prognostic biomarker and a predictor of immunotherapy response." (PMID 37301547, 2023). "This study found that HOXB9 is a robust pan-cancer prognostic biomarker that can effectively predict immunotherapy response." (PMID 37301547, 2023). "The TGF-β signaling pathway regulates HOXB9 expression and triggers the activation of EMT, which is associated with increased angiogenesis, lung metastasis, and radioresistance in cancer cells." (PMID 37301547, 2023). "From the individual cancer stages analysis, HOXB9 expression was higher in stage IV than in all other stages, suggesting that high HOXB9 expression is a poor prognostic factor." (PMID 36803556, 2023). "Subsequently, an investigation was conducted to analyze the correlation between HOXB9 and the prognosis of cancer patients." (PMID 37301547, 2023). "In our pan-cancer analysis, we found HOXB9 expression was elevated in these cancers, with roughly the same results." (PMID 36803556, 2023). "Our findings revealed a strong and consistent correlation between HOXB9 expression levels and cancer patient prognosis across multiple analyses, including OS, DSS, DFI, and PFI." (PMID 37301547, 2023). "Apart from playing a key role in embryonic development, HOXB9 is involved in the regulation of various human cancers." (PMID 36803556, 2023). "Overall, our findings confirmed that HOXB9 is a robust prognostic biomarker for various types of cancer and can effectively predict the response to immunotherapy." (PMID 37301547, 2023). "We further investigate the relationships between HOXB9 expression and immune cell infiltrations to demonstrate the links between HOXB9 and cancer immunity." (PMID 37301547, 2023). "The results revealed that high expression levels of HOXB9 were examined in most cancers except for KICH, KIRP, KIRC, LAMAL, and PRAD." (PMID 37301547, 2023). "The prognostic impact of HOXB9 in various cancers was further assessed by examining disease-free interval (DFI) and progression-free interval (PFI) outcomes." (PMID 37301547, 2023). "Studies have shown that the HOXB gene cluster contributes to cancer development; increased expression of HOXB3, HOXB6, HOXB7, HOXB8, and HOXB9 in LUAD patients is linked with poor overall survival (OS)." (PMID 36506331, 2022). "In this study, we observed that HOXB9 gene was not only significantly upregulated in cancer vs. normal colon, but its levels were significantly increased when KRAS mutations were present." (PMID 35216396, 2022). "As is known, HOXB9 is an important factor affecting disease progression and overall survival (OS) in cancer." (PMID 35216396, 2022). "Several studies have reported that HOXB9 overexpression increases the metastatic potential of cancer cells by activating an important process called epithelial-mesenchymal transition (EMT)." (PMID 35216396, 2022). "In both the Cochin dataset and in ACC samples from The Cancer Gene Atlas (TCGA), HOXB9 expression was significantly higher in C1A compared to C1B." (PMID 33214683, 2021). "This suggests that SSP1 and MMP9 are downstream target genes of the HOXB9/TGFβ/Smad2 pathway in the regulation of cancer metastasis." (PMID 34247196, 2021). "In this regard, recent findings emphasize the central role of the transcription factor HOXB9 in cancer development." (PMID 33171691, 2020).
cancer (continued). "A variety of mechanisms have been proposed to be responsible for the mis-regulation of HOXB9 during cancer progression." (PMID 33171691, 2020). "Several studies highlighted a role for HOXB9 in cancer progression, although both pro-tumoral and anti-tumoral effects have been described in different cancer types." (PMID 33411683, 2020). "In this review we will give a brief description of the HOX genes and their involvement in angiogenesis and cancer, with particular emphasis on HOXB9 as a possible novel target for anti-angiogenic therapy." (PMID 33171691, 2020). "Further research is warranted to analyze HOXB9v and HOXB9n individually and re-evaluate the true role of HOXB9 in cancer." (PMID 32104178, 2020). "HOXB9 upregulation has been reported in many types of cancers and it has been identified as a critical transcription factor involved in resistance to anti-angiogenic drugs." (PMID 33171691, 2020). "Because none of the previous studies on HOXB9 have considered the presence of HOXB9v, further research analyzing the two transcripts individually is warranted to re-evaluate the true role of HOXB9 in cancer." (PMID 32104178, 2020). "IHC analysis showed that platinum‐resistant cancer tissues more frequently had high HOXB9 expression than platinum‐sensitive cancer tissues." (PMID 31970886, 2020). "The recent elucidation of the critical and diverse roles HOXB9 plays in various cancers have led us to explore the mechanism of this gene's role in cancer progression." (PMID 32104178, 2020). "For example, high HOXB9 expression was shown to promote EMT via TGF-β signaling and was associated with shorter survival in hepatocellular and oral squamous cell carcinomas." (PMID 33411683, 2020). "Given the high expression level of HOXB9 in EC, we first investigated the effect of HOXB9 on cancer cell proliferation." (PMID 29724991, 2018). "HOXB9 was previously reported to regulate cancer progression, by targeting EMT via the transforming growth factor-β1/Smad2/Slug signaling pathway." (PMID 29724991, 2018). "In transwell and wound-healing assays, knocking down E2F3 abolished the ability of HOXB9 in enhancing cancer cell migration." (PMID 29724991, 2018). "In contrast, after overexpression of HOXB9 in the two cancer cells, the cell migration ability markedly increased." (PMID 29724991, 2018). "Through regulating EGR1 and HOXB9, miR‐192‐5p downregulated the angiogenic pathways in cancer cells." (PMID 28035762, 2017). "Pharmacological inhibition of β-catenin in GalNAc-T14-expressing cancer cells suppressed HOXB9 expression and invasion." (PMID 26544896, 2015). "There is now considerable evidence that miR-196a and HOXB9 exert a pro-tumorigenic influence in many cancers." (PMID 25860510, 2015). "When HUVECs and human dermal fibroblasts (HDFs) were co-cultured with cancer cell lines to mimic the microenvironment, HOXB9 significantly promoted cell proliferation." (PMID 24885802, 2014). "In addition, HOXB9 was significantly upregulated in the high-expression group across multiple cancer types." (PMID 41049442, 2025). "The overexpression of HOXB9 plays a dual role in various cancers." (PMID 38928496, 2024). "Taken together, this study revealed that HOXB9 might regulate tumorigenesis by affecting DNA repairment and DNA methylation across cancers." (PMID 37301547, 2023). "Overall, these findings strongly suggest that HOXB9 may have a significant impact on the cancers by interacting with immune cells." (PMID 37301547, 2023). "Overall, these results suggest that HOXB9 could serve as an important predictor of cancer patient prognosis." (PMID 37301547, 2023). "Similar correlation was observed between the grade of immune infiltration and HOXB9 expression across different cancer types in TCGA database with the XCELL, CIBERSORT and CIBERSORT-ABS algorithms, and the results revealed a positive correlation between HOXB9 and infiltration of mast cells in HNSCC." (PMID 37657018, 2023).